UBE2M (ubiquitin conjugating enzyme E2 M)
Diseases named in the same sentence as UBE2M in open-access papers (continued):
Sharing a sentence is not in itself a finding about the gene and the disease.
lupus (2 papers, 2023 to 2024). "Consistently, we also observed that loss of Ube2m significantly promoted DN T cell apoptosis and attenuated disease progression in pristane-induced lupus mice." (PMID 38221551, 2024). "Then, loss of Ube2m prominently blocked the neddylation of Cullin1, contributing to the Bim protein accumulation and finally promoting DN T cell apoptosis in lupus mice." (PMID 38221551, 2024). "Then double knockout (KO) lupus-prone mice (Ube2m-/-Bim-/-lpr) were generated and results showed that loss of Bim reduced Ube2m deficiency-induced apoptosis in DN T cells and reversed the alleviated lupus progression." (PMID 38221551, 2024). "To confirm that neddylation pathway regulated the homeostasis of DN T cells via Bim, we generated the double KO lupus-prone mice (Ube2m-/-Bim-/-lpr) and found that the deficiency of Bim disrupted the apoptosis of DN T cells for Ube2m deficiency and cannot inhibit the development of lupus." (PMID 38221551, 2024). "We have shown that loss of Ube2m promoted DN T cell apoptosis and contributed to alleviated lupus development, while the mechanism remained unknown." (PMID 38221551, 2024). "Here, we reported that neddylation inactivation with MLN4924, a specific inhibitor of NEDD8-activating enzyme E1 (NAE1), or genetic abrogation of Ube2m in T cells decreased DN T cell accumulation and attenuated murine lupus development." (PMID 38221551, 2024). "In vivo evidence establishing the crucial role of Ube2m in lupus development, we further explored how Ube2m regulated lupus progress." (PMID 38221551, 2024). "Meanwhile, compared with Bim-/-lpr mice, Ube2m-/-Bim-/-lpr mice also showed slightly remission on lupus development, indicating a Bim-independent manner of Ube2m on lupus development." (PMID 38221551, 2024). "However, we found that Ube2m expression and the neddylation of Cullin1 was significantly increased in lupus conditions, suggesting that the neddylation pathway activation was necessary for DN T cell abnormal survival in lupus progression." (PMID 38221551, 2024).
non-small cell lung carcinoma (2 papers, 2020 to 2022). A group of at least three distinct histological types of lung cancer, including non-small cell squamous cell carcinoma, adenocarcinoma, and large cell carcinoma. "Analyzing cell cycle-independent effects, we found that MLN4924 prevented the UBE2M-dependent neddylation of cullin 1, as recently observed in renal cell carcinoma, while cisplatin induced a strong decrease in proteasome activity, already reported in non-small cell lung cancer cells." (PMID 35197103, 2022). "Both cisplatin and carboplatin treatments in A549 and H1299, two human non-small cell lung cancer cell lines, led to the obvious accumulation of UBE2F in a dose-dependent manner, but not other neddylation components (e.g., E1: NAE1 and UBA3; E2: UBE2M; E3: RBX1 and RBX2)." (PMID 33184273, 2020).
ovarian carcinoma (2 papers, 2014 to 2024). A malignant neoplasm originating from the surface ovarian epithelium. "RNAi-mediated silencing of UBE2M, the primary E2 Nedd8 conjugating enzyme, caused significant reduction in the proliferation of ovarian cancer HEY cell line, consistent with the effects of MLN4924 on cell growth." (PMID 25025768, 2014).
prostate tumor (2 papers, 2022). "Expression profiling analysis suggested that the expression of UBE2M and OTUB1 was significantly increased in prostate tumor tissue samples compared with normal tissues." (PMID 35864871, 2022).
Sepsis (2 papers, 2025). Sepsis is defined as life-threatening organ dysfunction caused by a dysregulated host response to infection. "Compared with WT mice, mice with specific deficiency of UBE2M in macrophages (Lysm+Ube2mf/f mice) presented significant decreases in inflammatory responses and improvements in the survival rate after E. coli-induced sepsis." (PMID 39675717, 2025). "Given the critical role of UBE2M in macrophages in the pathogenesis of viral infections and the fact that Escherichia coli (E. coli) is a predominant causative pathogen of sepsis, we hypothesized that UBE2M in macrophages plays an important role in the development of E. coli-induced sepsis." (PMID 39675717, 2025). "In an Escherichia coli (E. coli)-induced sepsis mouse model, increased UBE2M expression in macrophages in liver and lung tissues postinfection was observed." (PMID 39675717, 2025). "The regulatory role of ubiquitin-conjugating enzyme E2 M (UBE2M) is evident in an Escherichia coli-induced sepsis mouse model." (PMID 40643532, 2025). "In this study, we investigated the effect of UBE2M in macrophages on E. coli-induced sepsis." (PMID 39675717, 2025). "First, the role of UBE2M in macrophages in sepsis induced by pathogens other than E. coli remains unknown and needs further investigation." (PMID 39675717, 2025). "Third, our study focused on the role of macrophages in E. coli-induced sepsis, and the involvement of UBE2M in other immune cells remains unknown." (PMID 39675717, 2025). "First, UBE2M expression in macrophages was upregulated in mice with E. coli-induced sepsis." (PMID 39675717, 2025). "In conclusion, our findings indicate that specific deletion of UBE2M in macrophages protects against E. coli-induced sepsis by downregulating the excessive inflammatory response, potentially providing a novel strategy against sepsis by targeting UBE2M." (PMID 39675717, 2025). "To clarify whether macrophage UBE2M affects the progression of sepsis, we crossed Lysm-Cre (Lysm+) mice with Ube2mf/f mice to obtain mice with UBE2M-deficient myeloid cells (Lysm+Ube2mf/f mice)." (PMID 39675717, 2025). "Notably, the bacterial loads in the lungs and livers of mice with E. coli-induced sepsis were similar regardless of macrophage-specific UBE2M deficiency." (PMID 39675717, 2025). "However, whether UBE2M is involved in bacterial-induced sepsis remains largely unknown." (PMID 39675717, 2025). "Mice with E. coli-induced sepsis presented a significant increase in the protein expression of UBE2M in the liver or lung but not in the kidney." (PMID 39675717, 2025).
viral infection (2 papers, 2023 to 2025). "In turn, IFN-I signaling–activated STAT1 enhances Trim21 transcription, leading to an increase in UBE2M degradation and a decrease in antiviral immunity in viral infections." (PMID 39675717, 2025). "Moreover, several novel genes score in the top 20 for multiple strains, including UBE2M, MBNL1, FBXW7, PCGF1, and PPP2CA, implicating those gene products in processes important for viral infection across HIV-1 strains." (PMID 36744886, 2023). "UBE2M, a crucial neddylation E2 enzyme downstream of NAE1, is instrumental in multiple cellular processes, such as cell cycle progression, the DNA damage response, and protein degradation, and is involved in the pathogenesis of various diseases, including cancers and viral infections." (PMID 39675717, 2025).
autoimmune disease (1 paper, 2023). A disorder resulting from loss of function or tissue destruction of an organ or multiple organs, arising from humoral or cellular immune responses of the individual to their own tissue constituents. "To verify the functional relationship between neddylation and CRLs in Treg cells, we compare the degree of autoimmune disorders and transcriptional alterations caused by Ube2m&Ube2f versus Rbx1&Sag deficiency in Treg cells." (PMID 37600496, 2023). "Double deletion of neddylation E2s Ube2m&Ube2f or E3s Rbx1&Sag in Treg cells leads to the impairment of suppressive function of Treg cells and results in severe autoimmune disorders, fully demonstrating the pivotal role of the neddylation-CRL axis in the maintenance of Treg cell fitness." (PMID 37600496, 2023).
bacterial sepsis (1 paper, 2025). "However, whether UBE2M is involved in the pathogenesis of bacterial sepsis remains unclear." (PMID 39675717, 2025).
breast tumor (1 paper, 2024). "In addition, we found that in 27 pairs of breast tumor tissues and normal tissues, UBE2M expression was significantly higher in breast tumor tissues than in paired adjacent normal tissues (p < 0.001)." (PMID 39138151, 2024).
Cirrhosis (1 paper, 2020). A chronic disorder of the liver in which liver tissue becomes scarred and is partially replaced by regenerative nodules and fibrotic tissue resulting in loss of liver function. "A high expression of UBE2M was positively correlated with cirrhosis (χ2 = 4.396, P = 0.036), tumor size (χ2 = 4.897, P = 0.027) and tumor number (χ2 = 5.614, P = 0.027)." (PMID 32012120, 2020). "In the present study, we reveal that UBE2M overexpression is positively correlated with cirrhosis, tumor size, tumor number, and poor prognosis." (PMID 32012120, 2020).
colitis (1 paper, 2022). Inflammation of the colon. "Indeed, the in vivo suppression assay using immune-deficient Rag1−/− mice clearly showed that very severe colitis, induced by injection of naive CD4+-T cells, cannot be inhibited by Ube2m-deficient Treg cells." (PMID 35641500, 2022).
E. coli infection (1 paper, 2025). "Second, macrophage-specific UBE2M deficiency attenuated E. coli infection–induced inflammation and organ injury in mice, whereas it did not affect E. coli clearance." (PMID 39675717, 2025). "To gain deeper insight into the altered response of UBE2M knockout in macrophages to E. coli infection, we performed gene set enrichment analysis (GSEA) utilizing KEGG gene sets." (PMID 39675717, 2025). "Consistently, confocal microscopy revealed a significant increase in UBE2M protein expression in liver and lung tissues 24 h after E. coli infection." (PMID 39675717, 2025). "Considering the substantial increase in UBE2M expression after E. coli infection, the organs of the liver and lung were selected for subsequent experiments." (PMID 39675717, 2025). "In our current study, we found that E. coli infection markedly promoted the upregulation of UBE2M in macrophages." (PMID 39675717, 2025). "In vitro experiments also revealed that UBE2M-deficient macrophages produced fewer proinflammatory cytokines after E. coli infection without hindering E. coli clearance." (PMID 39675717, 2025).
emphysema (1 paper, 2026). "In elastase-induced emphysema mouse models and in lung tissues from COPD patients, both UBE2M and VEGFR2 levels were markedly reduced, and Ube2m deficiency exacerbated lung injury." (PMID 42209461, 2026).
Hyperglycemia (1 paper, 2024). An increased concentration of glucose in the blood. "Additionally, the hyperglycemia of flies expressing CUL1 in the whole body and HSD flies were rescued by UBA3, UBE2M, or RBX1 knockdown." (PMID 38212312, 2024).
kidney injury (1 paper, 2025). Trauma to the kidney. "Our study elucidated a novel PRMT1/UBE2m/NEDD4/PPARγ signaling axis that drives renal lipid metabolic dysfunction in CaOx crystal-induced kidney injury." (PMID 40744915, 2025).
liver diseases (1 paper, 2026). "Bioinformatic analysis further reveals that genetic knockdown of NAE1, UBE2M, and URM1 affects overlapping genes associated with pathways controlling cellular response to stress conditions or with implications in liver diseases." (PMID 42056084, 2026).
lupus nephritis (1 paper, 2024). Glomerulonephritis in the context of systemic lupus erythematosus. "Furthermore, we also found that deficiency of Ube2m ameliorated lupus nephritis, including lessened total protein and albumin/ creatinine ratio, restored renal structures." (PMID 38221551, 2024).
Ovarian tumor (1 paper, 2022). "Ovarian tumor (OUT) deubiquitinase, ubiquitin aldehyde binding 1 (OTUB1) and ubiquitin conjugating enzyme E2 M (UBE2M) were predicted to be regulated by SNHG17 via competitively interacting with miR-23a-3p, miR-23b-3p, and miR-23c." (PMID 35864871, 2022).
pancreatitis (1 paper, 2021). Inflammation of the pancreas. "Clinically, UBE2M expression remarkably decreases in human CP tissues compared with normal specimens and the levels of CCL5 and M2 marker CD163 are negatively correlated with UBE2M intensity, suggesting that neddylation is involved in the pathogenesis of pancreatitis." (PMID 33723230, 2021).
tumor (28 papers, 2014 to 2026). "Sanger sequencing revealed one additional UBE2M mutation in the tumor with poor exome-sequencing quality." (PMID 36068196, 2022). "The researchers also found that GBM expressed higher levels of NEDD8 and related enzymes, such as NAE1, UBA3, and UBE2M, compared with normal brain tissue surrounding the tumor." (PMID 39564524, 2024). "Downregulation of UBE2M suppresses cancer cell proliferation by inducing cell cycle arrest, apoptosis or senescence, as demonstrated by the accumulation of multiple tumor suppressor proteins such as p21, p27 and NOXA." (PMID 39138151, 2024). "To verify the effects of UBE2M silencing on fulvestrant sensitivity in vivo, we established subcutaneous tumor models using MCF7 cells." (PMID 39138151, 2024). "The results showed that UBE2M expression was higher in ER+ tumor tissues than in ER- tumor tissues (p < 0.01)." (PMID 39138151, 2024). "Prediction of the mechanism of ibrexafungerp as a UBE2M inhibitor can inhibit the neddylation pathway which can reduce tumor-promoting factors and increase levels of tumor suppressors thereby improving the occurrence of tumors and prognosis." (PMID 38994207, 2024). "Silencing of UBE2M significantly inhibited tumor growth, volume and weight in nude mice with subcutaneous implantation of MCF7 cells." (PMID 39138151, 2024). "Many inhibitors targeting UBE2M-DCN1 interaction have been discovered to overcome the limitations of MLN4924 and tackle the crucial role of UBE2M on the neddylation pathway and tumor growth." (PMID 36690633, 2023). "Inhibition of UBE2M through siRNA treatment decreases cancer cell viability and clonogenic survival and inhibits tumor growth in vivo." (PMID 37717015, 2023). "In recent decades, increasing studies have shown UBE2M, also known as UBC12, to be an attractive anti-tumor target." (PMID 36690633, 2023). "UBE2M regulates tumor growth by modulating several cellular responses, such as DDR, senescence, or apoptosis." (PMID 36690633, 2023). "Altogether, the identification of the role of UBE2M in modulating anti-tumor immunity deserves further research." (PMID 36690633, 2023). "Creating an artificial scarcity of UBE2M leaves tumor cells more vulnerable to chemotherapy, radiotherapy, DNA damage, and apoptosis." (PMID 37717015, 2023). "To further investigate the exact contribution of NAE inhibition in the tumor, we employed shRNA-mediated knockdown of UBE2M in A20 cells." (PMID 37031300, 2023). "Meanwhile, UBE2M was found to be overexpressed in tumor tissues with a high Gleason score (Gleason's score = 8, 9, 10) compared with tumor tissues with a low Gleason score (Gleason's score = 6&7)." (PMID 35864871, 2022). "We were unable to find a second mutation in UBE2M in one tumor with a 19q loss and in NEDD8 in one tumor with an interstitial 14q deletion." (PMID 36068196, 2022). "In contrast, mice with UBE2M-overexpressing cells remarkably upregulated tumor growth compared to vector-transduced mice." (PMID 32012120, 2020). "Mice with UBE2M-silencing cells significantly suppressed tumor growth and weight compared to vector-transduced mice." (PMID 32012120, 2020). "The result demonstrated that UBE2M was also markedly elevated in HCC tissues compared with matched tumor-free tissues." (PMID 32012120, 2020). "Consistent with previous studies, our results show that UBE2M is remarkably elevated in tumor tissues, which is in concordance with TCGA dataset." (PMID 32012120, 2020). "Further analysis revealed that sixty-two patients have upregulated UBE2M expression in HCC compared to the non-tumor tissues." (PMID 32012120, 2020). "We first demonstrated that the neddylation pathway is activated in most OS cells, as evidenced by comparative analysis of NAE1 and Ube2M levels in OS tumor tissues and in healthly bone tissues." (PMID 27223074, 2016). "UBE2M has been shown to crucially regulate the tumor-suppressive cell cycle inhibitors." (PMID 36690633, 2023).
tumor (continued). "Targeting UBE2M to influence tumor growth by either modulating several biological responses of tumor cells (such as DNA-damage response, apoptosis, or senescence) or regulating the anti-tumor immunity holds strong therapeutic potential." (PMID 36690633, 2023). "Indeed, overactivation of CRLs has been characterized in tumor growth and progression and the enzymes implicated in the neddylation pathway (e.g., NAE1/UBA3, UBE2M/UBE2F, NEDD8 E3 ligases) are often overexpressed in different human cancers, including MM." (PMID 37460534, 2023). "UBE2M functions as an E2 NEDD8-conjugating enzyme and plays a critical role in the process of protein neddylation, which has been proven to be associated with antitumor immunity and tumor microenvironment modification." (PMID 35864871, 2022). "In addition, tumor sizes measured by caliper were significantly reduced in the mice group bearing UBE2M-depleted HepG2 cells compared to untreated control group by monitoring for 39 days, which was confirmed by evaluation of isolated tumors from mice." (PMID 34638383, 2021). "In contrast, UBE2M knockdown showed a powerful effect in inhibiting tumor growth and metastasis." (PMID 33827629, 2021). "Intensive studies have proven that NEDD8 and enzymes of the neddylation pathway (e.g., NAE1/UBA3, UBE2M/UBE2F, and NEDD8-E3 ligases) are often overexpressed in multiple human cancers, which are associated with tumor progression and predict poor patient survival." (PMID 33184273, 2020). "Thus, induction of apoptosis or senescence establishes UBE2M as a promising anti-tumor target." (PMID 36690633, 2023). "Currently, studies have shown that multiple inhibitors targeting the interaction between UBE2M and Defective In Cullin Neddylation 1 (DCN1) show certain anti-tumor effects." (PMID 39564524, 2024). "Consistently, the combination of UBE2M silencing and fulvestrant increased the accumulation of the cell cycle inhibitors p21 and p27 and the pro-apoptotic protein NOXA in tumor cells." (PMID 39138151, 2024). "UBE2M, a NEDD8-conjugating enzyme, is dysregulated in various human cancers and promotes tumor cell proliferation." (PMID 39138151, 2024). "This review highlights the most recent advances in the roles of UBE2M and UBE2F in tumor progression, indicating these E2s as two promising anti-tumor targets." (PMID 36690633, 2023). "In summary, the current research offers profound insights into the role of UBE2M and UBE2F in tumor progression, which is highly conducive to aiding the development of targeted inhibitors with higher potency and selectivity." (PMID 36690633, 2023). "Multiple inhibitors that target the interaction between UBE2M and defective cullin neddylation protein 1 (DCN1), a co-E3 for neddylation, exhibit promising anti-tumor effects." (PMID 36690633, 2023). "Specifically, 90% (36/40) of the OS tumor samples had high levels of NAE1, and 95% (38/40) had high levels of Ube2M." (PMID 27223074, 2016). "In-depth elucidation of the mechanisms of these E2s may provide more in-depth knowledge for targeting UBE2M and UBE2F as attractive anti-tumor therapy." (PMID 36690633, 2023). "Moreover, UBE2M-mediated protein neddylation is essential for multiple cellular responses, such as DNA-damage response (DDR), apoptosis, senescence, and anti-tumor immunity." (PMID 36690633, 2023). "Multivariate analysis showed that upregulated UBE2M expression could be a significant factor for predicting poor DFS (P = 0.008) when UBE2M expression level, TNM stage, and tumor size were included based on univariate analysis." (PMID 32012120, 2020).